CEP20 (centrosomal protein 20)
Description:
Involved in the biogenesis of cilia. Required for the recruitment of PLK1 to centrosomes and S phase progression.
Synonyms: C16orf63; FOPNL; FOR20; PHSECRG2; DKFZp686N1651; FLJ31153
Tractability: PROTAC: ubiquitination databases record sites on it.
Gene: Protein-coding gene on chromosome 16 (15,865,719 to 15,888,644, reverse strand). Ensembl gene ENSG00000133393.
Subcellular location: Cytoplasm, cytoskeleton, microtubule organizing center, centrosome, centriole; Cell projection, cilium; Cytoplasm, cytoskeleton, cilium basal body; Cytoplasm, cytoskeleton, microtubule organizing center, centrosome; Cytoplasmic granule; Cytoplasm, cytoskeleton, microtubule organizing center, centrosome, centriolar satellite
Subcellular location (Human Protein Atlas): Basal body; Centriolar satellite; Centrosome; Nucleoplasm
Gene Ontology:
Molecular function: identical protein binding; protein binding
Biological process: cilium assembly; microtubule anchoring
Cellular component: centriolar satellite; centrosome; ciliary basal body; motile cilium; centriole; cilium; microtubule organizing center
Genetic constraint (gnomAD): Loss-of-function variants: 16 observed, 15.31 expected, observed/expected ratio (o/e) 1.05, 90% interval 0.71 to 1.58. The upper end of that interval is the gene's LOEUF score, 1.58, which puts it in group 6 of 6, group 1 being the genes least tolerant of losing a copy. Missense variants: 189 observed, 182.14 expected, observed/expected ratio (o/e) 1.04, 90% interval 0.92 to 1.17. Synonymous variants: 72 observed, 70.6 expected, observed/expected ratio (o/e) 1.02, 90% interval 0.84 to 1.24.
Homologues: Orthologues: chimpanzee CEP20 (98% identical), macaque CEP20 (97% identical), guinea pig CEP20 (85% identical), rabbit CEP20 (85% identical), pig CEP20 (83% identical), dog CEP20 (83% identical), mouse Cep20 (79% identical), rat Cep20 (63% identical), zebrafish cep20 (51% identical), tropical clawed frog cep20 (47% identical).
Diseases named in the same sentence as CEP20 in open-access papers:
CEP20 is named in the same sentence as 11 diseases in open-access papers, as found by Europe PMC text mining. Sharing a sentence is not in itself a finding about the gene and the disease. The quoted sentences say what the papers report.
lung adenocarcinoma (1 paper, 2023). A carcinoma that arises from the lung and is characterized by the presence of malignant glandular epithelial cells. "We utilized RNA interference to downregulate CEP20 in lung adenocarcinoma cell lines A549 and H1299 and lung squamous cell carcinoma cell lines H226 and H520." (PMID 37838783, 2023).
lung carcinoma (1 paper, 2023). "Our previous research has shown that CEP20 is a centrosomal protein and a newly identified microtubule-associated protein involved in ciliogenesis, indicating its potential as a new target for lung cancer treatment." (PMID 37838783, 2023). "Overall, our findings provide a new target for targeted therapy of non-small cell lung cancer, and the potential utility of CEP20 in lung cancer diagnosis and treatment deserves further exploration at the molecular, cellular, animal model, and clinical pathology dimensions." (PMID 37838783, 2023). "In this study, we revealed that CEP20 promotes malignant behavior in lung cancer cells by affecting microtubule assembly, highlighting its potential as a new promising drug target for the treatment of lung cancer." (PMID 37838783, 2023).
cancer (2 papers, 2020 to 2023). A tumor composed of atypical neoplastic, often pleomorphic cells that invade other tissues. "In this study, we demonstrated that centrosomal protein 20 (CEP20) is upregulated in NSCLC tissues and associated with cancer invasion metastasis." (PMID 37838783, 2023). "To examine the expression level of CEP20 in NSCLCs, we collected tumor tissues and paired para-carcinoma tissues of patients with NSCLC from the Zhejiang Cancer Hospital." (PMID 37838783, 2023). "Western blot analysis of 113 pairs of tissues revealed a significantly higher level of CEP20 protein in 93 tumor tissues compared to their matched para-carcinoma tissues." (PMID 37838783, 2023). "All these biological processes are closely related to the development of malignant tumors, indicating that the high expression of CEP20 promotes protein synthesis and energy metabolism in NSCLC cells, leading to further aggravation of malignant tumor behaviors." (PMID 37838783, 2023).
tumor (1 paper, 2023). "Statistical analysis of patients’ clinical data demonstrated a significant correlation between CEP20 protein level and tumor invasion, lymphatic metastasis, and distant metastasis." (PMID 37838783, 2023). "Our analysis of public databases and patient samples revealed that the mRNA and protein expression of CEP20 in the tumor samples is higher than in the adjacent normal samples." (PMID 37838783, 2023). "Our future experiments will aim to better understand the influence of CEP20 in NSCLC tumorigenesis and metastasis using tumor xenograft models." (PMID 37838783, 2023).
CEP20 also shares sentences with these, for which no sentence is quoted: ciliopathies (2 papers); congenital blindness (1); lung squamous cell carcinoma (1); myeloproliferative disorder (1); non-small cell lung carcinoma (1); oral-facial-digital syndrome (1); schizophrenia (1).